FOXO4 (forkhead box O4)
Diseases named in the same sentence as FOXO4 in open-access papers (continued):
Sharing a sentence is not in itself a finding about the gene and the disease.
tumor (continued). "Retroviral expression of FOXO4 resulted in reduction of tumor formation in five of eight mice." (PMID 32214089, 2020). "While mouse knockout studies suggest its importance as a tumour suppressor, whether FOXO4 is altered in a broad range of human cancers is currently unknown." (PMID 28945225, 2018). "In cancer, FOXO4 has been suggested to be a tumor metastasis suppressor." (PMID 27976702, 2016). "Here, we report that FOXO4 is involved in the miR-150-induced tumor cell metastasis." (PMID 27976702, 2016). "The FOXO family members, FOXO1, FOXO3a and FOXO4, are ubiquitously-expressed transcription factors that function as tumor suppressor proteins through their ability to repress the expression of genes encoding proliferative, survival or anti-differentiation functions." (PMID 24983969, 2014). "Overall, GCs showed a lower expression level of FOXO4 in metastatic lesions compared to the corresponding primary tumor samples (Figures 1A3-A4).The expression levels of FOXO4 were also examined by western blot and RT-PCR in GC and adjacent normal tissues obtained from eight patients." (PMID 24886657, 2014). "Taken together with the current study, these findings support the notion that FOXO4 may influence tumor proliferation, migration, and invasion via multiple mechanisms, including metabolic reprogramming, activation of tumor‐suppressive pathways, or direct induction of cancer cell apoptosis." (PMID 41438489, 2025). "While reduced levels of FOXO4 might indicate malignancy, the weak or absent protein expression limits its primary use as diagnostic tumour marker." (PMID 38792023, 2024). "Additionally, elevated expression of FOXO4 expression inhibited tumor cell growth, invasion, and metastasis in vitro and in vivo, indicating that FOXO4 may play a role in GC progression and metastasis." (PMID 24886657, 2014). "It serves as an E3 ligase for histone deacetylase 3 (HDAC3), forkhead box O4 (FOXO4), and insulin-like growth factor 1 receptor (IGF-1R), affecting cellular migration, metabolic adaptation, and tumor growth." (PMID 41170373, 2025). "Our previous research showed that FOXO4, IRF8, and LEF1 were differentially expressed (via RNA sequencing) in canine OSA compared to patient-matched non-tumour tissue." (PMID 38792023, 2024). "hTERT‐RdRP activity was involved in the expression of various genes such as Forkhead box O4 (FOXO4), a tumor suppressor gene, by preventing proper cell cycle." (PMID 35094384, 2022). "In tumor cells, the PI3K/AKT signaling pathway is abnormally active, resulting in changes in FOXO4 expression." (PMID 34123834, 2021). "In a study of cholangiocarcinoma, FOXO4 was shown to mediate the EMT process, thereby affecting tumor progression and metastasis." (PMID 34123834, 2021). "To further verify the role of FOXO4 and APC2 in tumor invasion and metastasis in vivo, we injected four groups of SW620 cells (normal, OE-FOXO4, sh-APC2, OE-FOXO4 + sh-APC2) into the spleen and liver of nude mice, respectively." (PMID 34631691, 2021). "Both FOXO4 and APC2 were expressed in normal tissues adjacent to carcinoma but less in tumor lesions." (PMID 34631691, 2021). "The tissue microarray test results in 139 patients with CRC indicated that both FOXO4 and APC2 were downregulated significantly in CRC tumor lesions than normal tissue adjacent to carcinoma." (PMID 34631691, 2021). "FOXO4 mRNA expression was remarkably correlated with the patients' individual HNSCC clinical stage and tumor pathological grade." (PMID 34055579, 2021). "Ectopic expression of FOXO4 in Control-CRISPR 293T cells also showed the same trend to delay cell proliferation and reduce tumor formation." (PMID 32214089, 2020). "To demonstrate the impact of CSN6‐COP1 axis in regulating FOXO4 and subsequent gene expression of SGOC genes in vivo, we performed mouse xenograft cancer studies and demonstrated that CSN6 knockdown suppressed tumor growth." (PMID 33101846, 2020).
tumor (continued). "The members of the FOXO subclass (FOXO1, FOXO3, FOXO4 and FOXO6) are involved in a wide range of key biological processes including apoptosis, cell cycle, stress resistance, tumor resistance, differentiation, and metabolism." (PMID 31450545, 2019). "PTEN is a well-established tumor suppressor and increasing studies have suggested it inhibits tumor growth through upregulating FOXO family members such as FOXO3 and FOXO4." (PMID 30064475, 2018). "The overexpression of FOXO4 was found in these surviving cells, and DLBCL patients with FOXO4-positive tumor cells had poor prognosis." (PMID 27911272, 2017). "Moreover, the Forkhead box class O (FoxO) family of transcription factors is composed of FoxO1/FKHR, FoxO3/FKHRL1, FoxO4/AFX, and FoxO6, which regulate cellular homeostasis, autophagy, angiogenesis, tumour growth, and metastasis." (PMID 37174088, 2023). "FOXO4 is a factor regulating the cellular homeostasis of cancer cells, rather than just a tumor suppressor." (PMID 34631691, 2021). "The studies also imply that targeting CSN6, FOXO4, or SGOC pathway could be a strategic design in inhibiting tumor growth." (PMID 33101846, 2020). "These tumor samples were classified into four groups on the basis of the expression levels: high CSN6 and low FOXO4 expression, high CSN6 and high FOXO4 expression, low CSN6 and low FOXO4 expression, and low CSN6 and high FOXO4." (PMID 33101846, 2020). "Furthermore, we validated that miR-150 promoted tumor cells metastasis and EMT via FOXO4-mediated regulation of NF-κB/snail/YY1/RKIP circuitry, which consequently triggered the down-regulation of E-cadherin." (PMID 27976702, 2016). "The results revealed a significant decrease in the sizes of xenografts resulting from FOXO4 up-regulated cells.To further explore the role of FOXO4 in tumor metastasis in vivo, we implanted SGC7901-NC and SGC7901-FOXO4 cells into nude mice through the lateral tail vein." (PMID 24886657, 2014). "Importantly, we demonstrated that the half-lives of endogenous FOXO4 as well as FOXO3A are relatively longer in LMB-treated HCT-116 K-RAS (WT/−) cells, suggesting that mutant K-RAS is required for the destabilization of multiple FOXO tumour suppressors." (PMID 28945225, 2018). "Therefore, reduced tumor p27 expression is not due to a reversal of the effect of miR-106a~363 on Foxo3 and Foxo4 transcription." (PMID 28881594, 2017). "Therefore, although FOXO4 expression was not expected in bone, its expression and its downregulation in other tumours, including OSA, as shown in the present research, support its role relating to tumour suppression, and the subsequent growth and progression where it is downregulated." (PMID 38792023, 2024).
cancer (72 papers, 2012 to 2025). A tumor composed of atypical neoplastic, often pleomorphic cells that invade other tissues. "Several studies have shown an association between reduced FOXO4 expression and heightened cancer development." (PMID 39085238, 2024). "It seems that VS1, already exhibiting genomic instability, undergoes a near whole-genome doubling as well as acquires new mutations in cancer-related genes (FOXO4, GNAQ, PDGFRB), thereby completing the malignant transformation." (PMID 34816314, 2022). "Our findings indicate that phosphorylation of hTERT T249 regulates FOXO4 expression negatively by the RdRP activity in cancer cells and is implicated in pivotal event for carcinogenesis." (PMID 32214089, 2020). "For instance, the expression of FoxO4 protein induced cell cycle arrest in p27‐deficient cells by inhibiting cyclin D2, demonstrating the physiological relevance of carotenoids‐activated, FoxO‐induced cell cycle arrest in the treatment of cancer." (PMID 40161411, 2025). "The progression of several kinds of cancer is closely associated with Forkhead box O4 (FOXO4)." (PMID 34631691, 2021). "In CRC, circZFR dynamically regulates the expression level of downstream FOXO4 by binding to miR-532-3p, thereby promoting apoptosis and inhibiting cell cycle progression, thus exerting a certain anti-cancer effect." (PMID 41158508, 2025). "FOXO4, a member of the forkhead box transcription factor family, has received increasing attention in cancer research in recent years." (PMID 40149900, 2025). "This further enhances the distribution of forkhead box O1a (FoxO1a) and forkhead box O4 (FoxO4) and triggers cancer development and metastasis." (PMID 41198664, 2025). "Further, cellular senescence mediated by p21WAF1/Cip1 is suppressed by the lncRNA GUARDIN through a LRP130-PGC1a-FOXO4 signaling axis in various cancer types whereas p21WAF1/Cip1 plays rather an ancillary role in inducing SAL-mediated senescence in PCa." (PMID 39676172, 2024). "Despite its context-dependent roles in cancer development, FOXO4 involvement in cell cycle regulation and DNA repair renders it a potential therapeutic target." (PMID 38702629, 2024). "We analyzed data from the GEO database and also found that FOXO4 is significantly downregulated in NSCLC cancer tissues." (PMID 39085238, 2024). "The spontaneous malignant transformation was characterized by a near-total whole-genome doubling, disappearance of NF2 mutation and new mutations in three cancer-related genes (GNAQ, FOXO4 and PDGFRB)." (PMID 34816314, 2022). "Both FOXO3 and FOXO4 were shown to be involved in maintaining the self-renewal capacity of HSCs and cancer stem cells." (PMID 35406686, 2022). "Transcriptional factor FOXO4 has been reported to regulate various genes involved in cell cycle, apoptosis, metastasis, and metabolism in cancer cells." (PMID 35650605, 2022). "IHC staining of cleaved caspase 3 revealed that FOXO4-DRI enhanced cancer cells’ radiosensitivity by promoting cell apoptosis in vivo." (PMID 34877934, 2021). "Taken together, our results reveal that peptides can be generated to specifically target and eliminate FOXO4+ senescent cancer cells, which has implications for eradicating residual disease and as a combination therapy for frontline treatment of cancer." (PMID 34689087, 2021). "By rationally designing a senolytic to FOXO4, we showed that we can eliminate senescent cancer cells and use combination treatments for senescence induction and apoptosis of cancer cells resulting in increased survival." (PMID 34689087, 2021). "In mammalians, the Foxo subfamily includes four genes of forkhead box-O transcription factors (Foxos), Foxo1, Foxo3, Foxo4, and Foxo6 that play a key role in cancer." (PMID 35178394, 2021).
cancer (continued). "EGF‐mediated downregulation of FOXO4 rewires cancer metabolic programming via enhancing the expression of serine‐glycine‐one‐carbon genes." (PMID 33101846, 2020). "To corroborate the effects of FOXO4 expression in cancer cells, we established stable cell lines introduced with pBABE-hygro (pBh) control vector or FOXO4-expressing retroviral vector (pBh-FOXO4) in HeLa cells and 293T cells." (PMID 32214089, 2020). "Further developing inhibitors that hinder EGF/CSN6/COP1‐mediated FOXO4 degradation and functions can be a strategy for rational cancer therapy." (PMID 33101846, 2020). "For example, MMP2, MMP3, and MMP9 are direct or indirect target genes of FoxO3a in endothelial as well as cancer cells, and FoxO4 upregulated MMP9 expression in smooth muscle cells stimulated by tumor necrosis factor‐α (TNF‐α) by an indirect mechanism." (PMID 32790044, 2020). "Further, it is shown that CSN6‐COP1‐FOXO4 axis is deregulated in cancer and that the protein expression levels of CSN6 and FOXO4 can serve as prognostic markers for cancers." (PMID 33101846, 2020). "Our understanding of the role of FOXO4 in inhibiting serine/glycine metabolism of cancer reveals therapeutic opportunities for cancer treatment." (PMID 33101846, 2020). "USP7 has been proposed as a therapeutic target in several cancers because it has many reported substrates with a role in cancer progression, including FOXO4, MDM2, N-Myc, and PTEN." (PMID 32210275, 2020). "Inhibition of this kinase by the experimental drug D4476, combined with clinically approved proteasome inhibitors, accumulates nuclear FOXO4 to perturb the growth of RAS-mutant cancer cells by promoting apoptosis induction." (PMID 28945225, 2018). "Taken together, our data strongly suggest that the D4476:Bortezomib-induced RAS-mutant cancer growth arrest/death is, in part, due to the blockade of FOXO4 tumour suppressor turnover." (PMID 28945225, 2018). "The mentioned observations suggest that both sets of genes (LEF1 down-regulated and FOXO4 down-regulated) are actually up-regulated in normal epithelial-mesenchymal transitions, while their expression remains unmodified or decreases in cancer cell lines." (PMID 28798381, 2017). "The SP1 gene is itself among the FOXO4 targets and was found to be up-regulated in cancer cell lines." (PMID 28798381, 2017). "Hallmark capabilities enabled by epithelial-mesenchymal transition include sustained proliferation, with cell cycle components controlled by SP1, LEF1, and FOXO4 up-regulated in cancer cell lines." (PMID 28798381, 2017). "(2007) reported functional redundancy of Foxo1, Foxo3, and Foxo4 in the regulation of lifespan and cancer in mice under the AL condition." (PMID 25808402, 2015). "Collectively, these results suggest that SIRT1 acts as a molecular switch that determines whether FOXO4-mediated senescence is sustained or bypassed in cancer cells." (PMID 41008982, 2025). "There are also reports of FOXO4 downregulation in cancer cells treated with 1% O2 or CoCl2." (PMID 37240290, 2023). "Notably, PI3K/AKT and MAPK are oncogenic signalling pathways that are usually activated in various cancers and target FoxO4 in similar ways to inhibit its anti‐cancer function." (PMID 33103284, 2021). "In cancer research, FOXO4 is often considered to have a role in impeding cell proliferation." (PMID 33238881, 2020). "Together, the regulatory circuit of CSN6‐FOXO4 axis could be recapitulated in mouse xenograft cancer model, and level of FOXO4 deregulation plays roles in affecting the outcome of tumorigenicity." (PMID 33101846, 2020). "Furthermore, we found that phosphorylation of hTERT at T249 regulates the expression of the tumor suppressor gene, FOXO4, in cancer cell lines." (PMID 32214089, 2020). "Notably, FOXO4 is annotated in this GO term and functions as tumor suppressor proteins in various cancers by preventing proper cell cycle regulation." (PMID 32214089, 2020).
cancer (continued). "Importantly, in these mouse xenograft cancer model studies, control tumors contain low levels of FOXO4 and COP1 while demonstrate relatively high levels of PHGDH and Glut1." (PMID 33101846, 2020). "In cancer biology, FOXO4 is often considered to exert tumor-suppressive effects." (PMID 33238881, 2020). "However, in the present study, it was observed that the FOXO4 had a role in enhancing the proliferation and migration of VSMCs, which was different from its role in cancer cells." (PMID 33238881, 2020). "In addition, FOXO proteins (FOXO1, FOXO3 and FOXO4) are putative targets for prevention cancer therapy-related drug resistance." (PMID 31450545, 2019). "As we know, oxidative stress generated by treatment of cells with H2O2 can activate the expressions of Foxo transcription factors (like Foxo1, Foxo3a, and Foxo4), which may interact with β-catenin to inhibit the apoptosis of cancer cells." (PMID 30627375, 2018). "In addition, mutant RAS coordinately elevates proteasome subunit expression and proteolytic activity to eradicate nuclear FOXO4 proteins from RAS-mutant cancer cells." (PMID 28945225, 2018). "To investigate whether CK1α directly phosphorylates FOXO4 proteins in RAS-mutant cancer cells, we generated a phospho-specific antibody that targets phosphorylated S265 and S268 of FOXO4 (p-FOXO4S265/268)." (PMID 28945225, 2018). "Importantly, dual inhibition of CK1α and the proteasome synergistically inhibited the growth of multiple RAS-mutant human cancer cell lines of diverse tissue origin by blockade of nuclear FOXO4 degradation and induction of caspase-dependent apoptosis." (PMID 28945225, 2018). "All together, these data show that the oncogenic inactivation of GSK3β by the delE746-A750EGFR or E545KPIK3CA cancer proteins significantly increases nuclear β-catenin pool in response to GD and enhances β-catenin- and FOXO4-dependent expression of genes involved in antioxidant stress response." (PMID 22662165, 2012). "The rational use of integrative machine learning models can significantly improve the probability of early detection of cancer, and in future studies, we will further explore whether FOXO4 can be one of the key markers for the diagnosis and treatment of BC based on the current results." (PMID 41438489, 2025). "Notably, FOXO4 inhibits SGOC pathway metabolic reprogramming of cancer." (PMID 33101846, 2020). "TET1/FOXO4 Axis: CRISPR-induced TET1 overexpression sequesters β-catenin in the cytoplasm, inhibiting Wnt signaling while stabilizing FOXO4 to regulate cancer stem cell (CSC) properties and EMT processes." (PMID 40951343, 2025). "We found that both EZH2-A and -B subtypes inhibited the expression of these four downstream cancer related genes (BMP2, PRODH, FOXO4, NPRL2), while EZH2-C exhibited the opposite effect." (PMID 39850359, 2025). "FOXO4 is down-regulated in GBM while its overexpression promotes apoptosis and inhibits the migration and invasion of cancer cells." (PMID 37208656, 2023). "In our study, TET1 suppresses cancer metastasis through decreasing the features of CSC and EMT by inhibiting Wnt/β-catenin signaling through transactivating FOXO4." (PMID 35805009, 2022). "NCAPG expression is increased in various cancers, including hepatocellular liver cancer, as an oncogene that stimulates cell proliferation and apoptosis through the PI3K/AKT/FOXO4 pathway." (PMID 35322101, 2022). "The FOXO transcription factor family contains four highly relevant members, namely, FOXO1, FOXO3a, FOXO4, and FOXO6, which are direct downstream targets of AKT and play important roles in cancer progression." (PMID 34183647, 2021). "To evaluate the process of cancer development in BxPC-3 CM-treated C2C12 cells, we analyzed STAT3, Akt, and FoxO4 phosphorylation by Western blot analysis." (PMID 33802674, 2021).